TNF (tumor necrosis factor)
Diseases named in the same sentence as TNF in open-access papers (continued):
Sharing a sentence is not in itself a finding about the gene and the disease.
coccidioidomycosis (continued). "Current recommendations prior to anti-TNF-α therapy include a chest x-ray, a tuberculin skin test and coccidioidomycosis serology." (PMID 17803815, 2007). "Physicians should be aware of the importance of travel history and potential for life-threatening coccidioidomycosis in patients receiving tumor necrosis factor inhibitors." (PMID 17803815, 2007). "Further studies regarding the incidence of coccidioidomycosis in patients on anti TNF-α therapies and the effectiveness of azole prophylaxis in this group are needed before definitive recommendations can be made." (PMID 17803815, 2007). "Likewise, dogs with coccidioidomycosis produced higher concentrations of TNF-α (p < 0.0001), IL-6 (p < 0.0001), GM-CSF (p = 0.03), IL-8 (p = 0.02), IFN-γ (p = 0.03), KC-like (p = 0.01), MCP-1 (p = 0.01), and IL-10 (p = 0.0004) with coccidioidal stimulation compared with unstimulated control." (PMID 36836327, 2023). "Additionally, B6D2F1 mice, which are intrinsically resistant to Coccidioides infection, when treated with anti-TNF Abs for only the first 14 days after infection, had decreased survival and increased lung and spleen fungal burdens compared with isotype-treated controls." (PMID 36166305, 2022). "The monocyte to macrophage differentiation in response to Coccidioides infection, although not previously measured, is consistent with prior studies that found high IL-6, IL-12, TNF and MIP-2 production by Coccidioides-infected peritoneal macrophages." (PMID 34436169, 2021). "Furthermore, studies have shown increases in cytokines such as interferon gamma (IFNγ), tumor necrosis factor alpha (TNFα), and interleukin (IL)-17 in mononuclear cells from bronchoalveolar lavage fluid (BALF) from patients with pulmonary coccidioidomycosis." (PMID 31572393, 2019). "In patients with pulmonary coccidioidomycosis, several cytokines were increased in high concentrations, including granulocyte-macrophage colony-stimulating factor (GM-CSF), interleukin-1β (IL-1β), interferon gamma (IFN-γ), IL-2, IL-13, and tumor necrosis factor alpha (TNF-α)." (PMID 37233224, 2023).
diabetic foot ulcers (19 papers, 2010 to 2025). "The authors suggest that chronic inflammation in patients with diabetic foot ulcers, supported by the increased level of TNF-α, is associated with an enhanced production of sVEGFR1 and consequently a reduction in VEGF level." (PMID 38473424, 2024). "This study aims to find the association between ApoA1, IL-10, TNF-α, and diabetic foot ulcers and whether their levels can assess the severity of the disease." (PMID 35836916, 2022). "However, the available data suggest that IL-6, CRP, and TNF-α measurements in diabetic foot ulcers could be valuable tools for patient risk stratification, as well as predictors for lower-limb amputation and perioperative risk of morbidity and mortality." (PMID 39596058, 2024). "Persistently elevated levels of proinflammatory cytokines such as IL-6, IL-1β, IL-8 and TNFα have been found in the wound bed fluids of patients with diabetic foot ulcers." (PMID 39941031, 2025). "Similar results were obtained in a clinical study on the effects of CAP on diabetic foot ulcers in which it was found that the concentration of IL-1, IL-8 and TNFα in the wound bed decreased after CAP treatment." (PMID 39941031, 2025). "This study aimed to assess how negative pressure occlusion drainage combined with silver ion dressing affects inflammatory cytokine levels (IL-6, TNF-α) and wound healing in patients with diabetic foot ulcer." (PMID 41393293, 2025). "Real-Time Polymerase Chain Reaction: RT-PCR for the gene expression of CD68, CD86, CD206, CD40, IL-6, IL-1β, and TNF-α revealed increased relative gene expression (normalized to housekeeping gene 18S) in diabetic foot ulcer tissues compared to control tissues." (PMID 36362563, 2022). "This study evaluated the association between Apo A1 and other inflammatory biomarkers like TNF-α and IL-10 and diabetic foot ulcers." (PMID 35836916, 2022). "In this study, by stimulating GD-HUVECs with a pro-inflammatory stimulus such as a low level of tumor necrosis factor-alpha (TNF-α), we have generated an environment like the one found in diabetic foot ulcer endothelium." (PMID 35866032, 2022). "Likewise, dracorhodin (a flavonoid from Dragon’s Blood) improved DFU outcomes via multi-pathway modulation: it dose-dependently enhanced collagen deposition and angiogenesis while reducing inflammatory cytokines (TNF-α, IL-6) and ROS levels in a diabetic foot ulcer model." (PMID 40728954, 2025). "In addition to their role in PDN, IL-6 and TNF-α may also contribute to the pathogenesis of diabetic foot ulcers." (PMID 39596058, 2024). "In diabetic foot ulcers (DFU), the release of IL-1β and TNF-α by numerous M1 macrophages inhibits keratinocyte migration, thereby delaying wound healing." (PMID 41465092, 2025). "In another study by Amini, a randomized clinical trial in Iran on 44 patients with diabetic foot ulcers, helium plasma jet treatment decreased the production of IL-1, IL-8, IFN-γ, and TNF-α and reduced the antimicrobial burden." (PMID 36240146, 2022). "Silver dressings enhance wound healing without toxicity and promote healing in diabetic foot ulcers by regulating inflammatory factors like IL-6 and TNF-α." (PMID 41393293, 2025). "In addition, TNF-α, IL-6, and IL-1β levels have been revealed to return to normal levels by propolis administration, and infections in diabetic foot ulcers have been proven to improve." (PMID 37542207, 2023). "It is possible, therefore, that experimental suppression of TNF-α affects fibrosis through mediation of TGF-β1 levels; similar effects were suggested in an earlier ABM of inflammation in the setting of chronic, non-healing diabetic foot ulcers." (PMID 25152891, 2014).
dyslipidaemia (19 papers, 2010 to 2024). "Lipid profile, disease activity, dyslipidaemia risk factors, and vascular measurements across the three visits for patients starting anti-TNFα therapy." (PMID 22824166, 2012). "A working model would hence place elevated TNF-α and hsCRP as indicators of systemic inflammation, and the pro-atherogenic state that occurs with dyslipidaemia would engender endothelial cell dysfunction and increased endothelial cell activation." (PMID 27483306, 2016). "The positive correlation between TNF-α (a pro-inflammatory cytokine) and lipoprotein (a) levels indicates a probable interrelationship between dyslipidaemia and inflammation in the pathogenesis of CAD." (PMID 20532435, 2010). "In addition, systemic inflammation has been proposed to be accompanied by dyslipidaemia, producing several proinflammatory factors (including tumour necrosis factor (TNF)-α and interleukin 6 (IL-6))." (PMID 26264374, 2015). "Furthermore, HOMA-IR index and serum cytokine levels (IL-6 and TNF-α) involved in dyslipidaemia were improved, and no toxicity appeared." (PMID 26264374, 2015).
Hashimoto thyroiditis (19 papers, 2014 to 2025). An autoimmune disorder caused by the production of autoantibodies against thyroid tissue. "One pathway is through a common inflammatory pathway involving factors such as interleukin-6 (IL-6), IL‐12, IL‐10 and tumor necrosis factor that were shown to be significantly higher in women with autoimmune hypothyroidism and euthyroid TAI+ women compared to TAI− controls." (PMID 39888679, 2025). "Chronic inflammation is also present in Hashimoto’s thyroiditis, an autoimmune thyroid disorder characterized by tissue damage, fibrosis, and the release of inflammatory cytokines including Interleukin 6 (IL-6), Tumor Necrosis Factor-alpha (TNF-α), and Interleukin 1 beta (IL-1β)." (PMID 40218202, 2025). "The proinflammatory cytokine concentrations of IL-8, IL-10, IL-1B, and TNF-α were found to be significantly increased in patients with Hashimoto’s disease, who have anti-thyroid peroxidase antibodies and/or anti-thyroglobulin antibodies as compared to age- and sex-matched controls." (PMID 37241088, 2023). "In Hashimoto’s thyroiditis, the immune response of Th1 lymphocytes predominates, which, together with macrophages, produce mainly pro-inflammatory cytokines, including INF-γ, TNF-α, IL-1, and IL-6." (PMID 37371976, 2023). "Inflammatory cytokines including IL-6, TNF-α and IFN-β have been found extensively in both thyroids and sera of patients with Hashimoto’s thyroiditis." (PMID 33304319, 2020). "We determined that patients with Hashimoto’s thyroiditis had substantial levels of IL-1B, IL-8, and IL-12 and TNF-α, but that the levels of IL-6 and IL-12 were non-significant compared to the healthy control group." (PMID 37241088, 2023). "The concentrations of IL-8, 10, IL-1B, and TNF-α were significant higher in patients with Hashimoto’s disease (p < 0.05), whereas the concentrations of IL-6 and 12 were non-significant among patients with Hashimoto’s disease as compared to healthy controls (p > 0.05)." (PMID 37241088, 2023). "Cytometric Bead Array (CBA) analysis of pro and anti-inflammatory cytokines (IFN-gamma, IL-2, IL-6, IL-17 A, TNF-alpha and IL-4, IL-10) was done in 15 PTC irrespective of Lymphocytic Thyroiditis (LT) and 16 Hashimoto’s Thyroiditis (HT) cases." (PMID 37563607, 2023).
Heat Stroke (19 papers, 1993 to 2025). A condition caused by the failure of body to dissipate heat in an excessively hot environment or during PHYSICAL EXERTION in a hot environment. "Our research findings also indicate significantly increased NF-κB expression in the liver of the DHC group compared with that in the NC group, indicating that heat stroke caused inflammatory responses in the body in a process involving TNF-α and IL-6." (PMID 38553498, 2024). "iNOS has been shown to be upregulated by lipopolysaccharide, IL-1, and TNF-α, all of which are elevated in heat stroke, thereby resulting in the production of substantial quantities of NO." (PMID 40703654, 2025). "In our results, TNF-α and IL-6 were rapidly increased upon infection and heat stroke which was also previously reported." (PMID 34092247, 2021). "Both CD34− PDMSCs and CD34+ HUCB equally attenuated heat stroke-induced overexpression of both IL-1β and TNF-α in rats." (PMID 29416747, 2018). "The plasma levels of pro-inflammatory cytokines such as TNF-α and IL-1β are elevated following heat stroke." (PMID 29416747, 2018). "Of note, during the 1 to 3 hour post-heat stroke induction period, serum concentrations of TNF-α, IL-6, IL-10, BUN, and creatinine were significantly lower in dogs that received HF than in dogs that did not receive HF." (PMID 25145441, 2014). "We found that in the 3 hours after the induction of heat stroke, serum concentrations of TNF-α, IL-6, IL-10, BUN, and creatinine continued to increase in the control group of dogs, but not in the group of dogs that subsequently received HF." (PMID 25145441, 2014). "The previous studies had also shown that heat stroke induced systemic and cerebral striatal productions of IL-1β and TNF-α in both rats and rabbits." (PMID 20937119, 2010). "Activated inflammation is evidenced by overproduction of pro-inflammatory cytokines (e.g., interleukin-1β (IL-1β) and tumor necrosis factor-α (TNF-α)) in circulation of heat stroke rats." (PMID 20937119, 2010). "The immediate treatment with HES alone and the combined agent at the onset of heat stroke attenuated the heat stroke-induced increased serum lipid peroxidation, as well as attenuating it increased the serum levels of IL-1β and TNF-α." (PMID 20937119, 2010). "The serum concentrations of inflammatory cytokines (such as IL-1β and TNF-α) are elevated in humans and animals with heat stroke." (PMID 20937119, 2010). "The authors reported recently that endotoxaemia mediated elevated levels of tumour necrosis factor (TNF-α) and interleukin-1α (IL-1α) were involved in the pathophysiology of acute heat stroke patients." (PMID 18475549, 1993). "Experimental studies in rodent heat stroke models demonstrate significant elevation of circulating ET-1 levels, with mechanistic analyses revealing that selective ET-1 receptor antagonism ameliorates thermoregulatory failure by attenuating TNF-α production." (PMID 40703654, 2025). "This reveals that an exaggerated anti-inflammatory cytokine response may worsen heatstroke outcomes, which is further demonstrated by IL-6 and TNF-α knockout mice showing higher classic heat stroke-related mortality." (PMID 39619011, 2024). "Previous studies have demonstrated that SMS treatment could ameliorate cerebral iNOS reactivity and NO production, and reduce serum levels of TNFα, IL-1β, and IL-6 in heat stroke rats." (PMID 39156108, 2024). "Pro-inflammatory cytokines including IL-1β, IL-6, and TNF-α are elevated in both infection and heat stroke, suggesting infection might prime a latent immune response that is synergistically driven by heat challenge and promoted severe pathology." (PMID 34092247, 2021). "In addition, administration of human umbilical cord blood cells (HUCBC) also increases the serum levels of IL-10 and decreases the levels of TNF-α during heat stroke." (PMID 32477247, 2020).
Heat Stroke (continued). "Both cell populations could improve outcomes following heat stroke by preventing the overproduction of pro-inflammatory cytokines including IL-1β and TNF-α." (PMID 29416747, 2018). "Therefore, in the present study, we investigated changes in serum concentrations and clearance of the pro-inflammatory factors TNF-α and IL-6 and the anti-inflammatory factor, IL-10, in dogs following the induction of heat stroke and HF." (PMID 25145441, 2014). "HF prevents heat stroke-induced increases in serum cytokine concentrations and is effective for clearing small molecular weight solutes from serum, but less effective for clearing larger molecular weight solutes, including TNF-α, IL-6, and IL-10." (PMID 25145441, 2014). "A second case report where NDPH was preceded by an acute clinical event also known to be associated with an elevation of TNF alpha, in this case heat stroke, and with no other secondary medical issues noted." (PMID 24364890, 2013). "The levels of both TNF-α and IL-1 receptors correlate well with severity of heat stroke." (PMID 20937119, 2010). "Indeed, as it is shown in the present results, an increase of serum IL-1β and TNF-α levels is observed in heat stroke rats." (PMID 20937119, 2010). "Furthermore, the present results show that treatment with the combined agent significantly attenuates the heat stroke-induced overproduction of IL-1β and TNF-α in the serum." (PMID 20937119, 2010). "The immediate administration of this combined agent might exert its protective effects by attenuating the increased plasma level of IL-1β and TNF-α during heat stroke." (PMID 20937119, 2010). "Our results indicated that following heat stroke, arterial hypotension, decreased cerebral blood flow, increased serum levels of IL-1β, TNF-α and MDA, and increased striatal dopamine, serotonin and hydroxyl radicals and increased of levels of glutamate, glycerol and lactate/pyruvate ratio developed." (PMID 20937119, 2010). "Serum concentrations of all solutes tended to increase with time after heat stroke in the control group, but decreased (BUN, creatinine) or remained relatively unchanged (TNF-α, IL-6, IL-10) with time in the HF group." (PMID 25145441, 2014). "Serum concentrations of interleukin (IL)-10, tumor necrosis factor (TNF)-α, IL-6, blood urea nitrogen (BUN) and creatinine were measured at baseline and 1, 2, and 3 h after heat stroke." (PMID 25145441, 2014). "Concentrations of the ischemic and damage markers, dopamine, serotonin, and hydroxyl radical productions in corpus striatum, and the serum levels of interleukin-1 beta, tumor necrosis factor-alpha and malondialdehyde (MDA) were observed during heat stroke." (PMID 20937119, 2010). "The level of TNF- experiences a significantly higher increase than under heat stroke experiment suggesting that LPS might not be playing a crucial role in the SIRS following the heat stroke protocol considered in this work." (PMID 24039931, 2013). "Furthermore, we also attempt to ascertain whether the neuroprotective effects of the combined agent treatment are associated with inhibition of cerebral release of glutamate, DA, 5-HT, hydroxyl radicals, and the serum IL-1β, TNF-α and malondialdehyde (MDA) levels during heat stroke." (PMID 20937119, 2010).
hemorrhagic stroke (19 papers, 2014 to 2025). A stroke caused by a bleed on the brain. "In the acute phase of hemorrhagic stroke, activated microglia contribute to the clearance of cellular debris and secrete pro‐inflammatory cytokines such as TNF‐α, IL‐1β, and IL‐6, which can exacerbate neuronal injury if persistently elevated." (PMID 41363028, 2025). "The levels of Il-6, IL-8 and TNF-α were increased in all cases of ischemic and hemorrhagic stroke that were tested." (PMID 35239818, 2022). "TNF, a cytokine related to a severe stage of systemic inflammation, is substantially raised in patients with ischemic and hemorrhagic stroke." (PMID 33082828, 2020). "Moreover, treatment with a first-in-class cofilin inhibitor attenuates microglial activation and nitric oxide and TNFα expression in an in vitro model of hemorrhagic stroke." (PMID 37106830, 2023). "Traditionally, pro-inflammatory cytokines, such as IL-6 and TNF-α as well as IL-1β and matrix metalloproteinases (MMPs), have been studied in a wide range of medical conditions including ischemic and hemorrhagic stroke as a surrogate for predicting poor outcomes." (PMID 35927663, 2022). "Biomarkers such as tumor necrosis factor alpha (TNFα), C-reactive protein (CRP), homocysteine (Hcy), and vascular endothelial growth factor (VEGF) have previously been associated with differential findings in ischemic and hemorrhagic stroke." (PMID 33585095, 2021). "In contrast, after haemorrhagic stroke, only TNF-α was significantly upregulated at 24 h." (PMID 33097782, 2020). "Therefore, the TNF signaling pathway may play an important role in ferroptosis following hemorrhage stroke." (PMID 34163322, 2021). "The overexpression of HSP70 reduced the production of tumor necrosis factor-α (TNFα) and IL1 and has been shown to attenuate BBB disruption in a model of hemorrhagic stroke." (PMID 33066304, 2020). "The finding that anti-TNF therapy did not have an effect on lesion volume, but improved behavioral outcome in the present study, has previously been shown in an animal model of hemorrhagic stroke where they used etanercept." (PMID 25498129, 2014).